APOB (apolipoprotein B)
Diseases named in the same sentence as APOB in open-access papers (continued):
Sharing a sentence is not in itself a finding about the gene and the disease.
hyperlipidemia (continued). "Similarly, PCSK9 and APOB were associated with hyperlipidemia in the UK Biobank." (PMID 39474612, 2024). "The proband’s younger brother (II3) had nephrotic syndrome, and laboratory examination showed proteinuria, hypoalbuminemia, hyperlipidemia and a high level of apoB; the same apoE gene mutation was also detected, so we cannot exclude that the patient may be diagnosed with LPG." (PMID 31092271, 2019). "By integrating network pharmacology, MR analysis, MD, and MDS, our findings suggest that APOB is a key target of naringenin in the treatment of hyperlipidemia." (PMID 39474612, 2024). "We also confirmed a causal relationship between APOB, PCSK9, and NCAN and hyperlipidemia in the external dataset." (PMID 39474612, 2024). "First, we double downgraded for indirectness for apoB since there was only one trial comparison in predominantly females with hyperlipidemia, which lacks reproducibility and leads to poor applicability of the results to the general adult population." (PMID 39519598, 2024). "A further aim was to establish any potential relationship between ApoB and serum lipid parameters, then to distinguish normal, borderline, and pathological results, to evaluate ApoB as useful in practice to improve hyperlipidemia diagnosis." (PMID 38392258, 2024). "Our study suggests that naringenin binds stably to APOB, potentially contributing to its therapeutic effects in treating hyperlipidemia." (PMID 39474612, 2024). "Having established the growing value of ApoB detection in hyperlipidemia, we performed the present study to assess ApoB serum concentrations in Italian hyperlipidemic children and adolescents and their siblings." (PMID 38392258, 2024). "The intersection of two modules and Mendelian randomization result identified APOB as a key regulatory target of naringenin in the treatment of hyperlipidemia." (PMID 39474612, 2024). "As expected, 3 months of AGBR diet significantly elevated apolipoprotein-A1 levels; however, it reduced apolipoprotein-B levels in patients with hyperlipidemia (p < 0.05)." (PMID 38826585, 2024). "AGBR relieves hyperlipidemia in patients, as evidenced by reduced levels of triglycerides, total cholesterol, low-density lipoprotein cholesterol, and apolipoprotein-B, and elevated levels of high-density lipoprotein cholesterol and apolipoprotein-A1." (PMID 38826585, 2024). "In our study, post-prandial secretion of VLDL, the predominant post-prandial lipoprotein associated with hyperlipidaemia, was lower in participants homozygous for TM6SF2 or PNPLA3, but fasting ApoB levels were normal." (PMID 37484212, 2023). "Results suggested that CM1 improved hyperlipidemia through the downregulation of the plasma level of apolipoprotein B48, modulating the expression of certain significant genes and proteins in liver and suppressing preadipocyte differentiation in 3T3-L1 cells." (PMID 37836659, 2023). "Apolipoprotein B has rarely been used as an independent indicator of hyperlipidemia or as a predictor of changes in bone mineral density." (PMID 36568987, 2022). "Corticosteroid-treated female patients with SLE have manifestations of higher levels of plasma ApoB as well as hyperlipidemia including VLDL, TG and LDL." (PMID 35371016, 2022). "From experimental animal models, mice that were overexpressing ApoB exhibited hyperlipidaemia, neurodegeneration, amyloid plaques accumulation, and cognitive impairment, similar to transgenic mouse model overexpressing proteins related to Alzheimer's disease." (PMID 36247924, 2022). "Meta-analysis of the data indicated that the C allele of APOA5 1131 T > C, the A allele at APOA1-75 bp, the APOB XbaI T allele, and the ε2 and ε4 allele of APOE were each a risk factor for susceptibility for hyperlipidemia." (PMID 33836655, 2021).
hyperlipidemia (continued). "Meta-analysis of the data indicated that APOA5–1131 T > C, APOA1 -75 bp, APOB XbaI, and APOE gene polymorphisms were significantly associated with hyperlipidemia, with OR values of 1.996, 1.228, 1.444, and 1.710, respectively." (PMID 33836655, 2021). "Of the existing apolipoprotein candidate genes, researchers have correlated APOA1, APOA5, APOB, and APOE gene polymorphisms with hyperlipidemia." (PMID 33836655, 2021). "Research on rats has shown that the Banxia Baizhu Tianma decoction can reduce serum TC, TG, LDL cholesterol, apolipoprotein B, superoxide dismutase, and malondialdehyde in rats with hyperlipidemia." (PMID 34036306, 2021). "APOB-100-overexpressing transgenic mice show hyperlipidemia and numerous studies support that an elevated serum cholesterol level induced by a high-fat/high-cholesterol diet leads to cardiovascular dysfunction in these animals." (PMID 33919597, 2021). "Compared with the fasting state, postprandial hyperlipidemia is related to increasing levels of chylomicron remnants, which include TG and apolipoprotein B-48." (PMID 32200533, 2020). "In conclusion, our study suggested that the significant associations were found between hyperlipidemia, the serum levels of TC, HDL, LDL and APOB and PCV." (PMID 31877157, 2019). "Apolipoprotein B (Apo B) levels are generally tested for patients with cardiac diseases and/or hyperlipidemia." (PMID 29487710, 2018). "Ablation of Ces1g expression in vivo results in both postabsorptive (fasting) and postprandial hyperlipidemia and augmented circulating apoB concentrations due to increased secretion of VLDL and chylomicrons." (PMID 28677105, 2018). "ApoM was also positively correlated with apoB in the T2DM with hyperlipidaemia group (r = 0.220, P <0.05) and healthy controls (r = 0.351, P <0.001)." (PMID 27633510, 2016). "This study found that 4 g of fish oil consumption for 3 months effectively decreased serum total cholesterol, triglyceride, apolipoprotein B and glucose concentrations in an Asian population with NAFLD associated with hyperlipidemia." (PMID 26226139, 2015). "Inhibiting apoB synthesis with antisense compounds has found a place in the management of some cases of hyperlipidemia, despite modest increases in liver TG stores." (PMID 25806685, 2015). "In this study, we concluded that EPA and DHA inhibit CM and VLDL assembly and secretion in intestinal epithelial cells partly via reducing TG and apoB synthesis, which alleviated hyperlipidemia by directly reducing absorbed TG secretion from enterocytes." (PMID 24987699, 2014). "A more recent study showed that n-3 fatty acids decreased postprandial apolipoprotein B-48 concentrations by 22% suggesting that the reduction in postprandial lipemia with n-3 fatty acids are also related to improvements in chylomicron metabolism." (PMID 25061524, 2014). "Despite the small number of female participants, these results indicated that fasting values of RemL-C, RLP-C, RLP-TG, and TG/apoB in addition to TG are useful markers of postprandial hyperlipidemia in men and women." (PMID 23110373, 2012). "Fasting TRL-related values, especially RemL-C, RLP-C, RLP-TG, and TG/apoB are useful predictors of postprandial hyperlipidemia in young healthy individuals." (PMID 23110373, 2012). "Fasting triglyceride-rich lipoprotein-related values, especially RemL-C, RLP-C, RLP-TG, and TG/apoB are useful predictors of postprandial hyperlipidemia in young healthy individuals." (PMID 23110373, 2012).
hyperlipidemia (continued). "The use of ultra-small plant phospholipids can reduce the level of non-HDL-C (non-high-density lipoprotein (HDL) cholesterol), triglycerides (TG), apolipoprotein B, total protein, and very low-density lipoprotein cholesterol, which allows them to be used in the treatment of combined hyperlipidemia." (PMID 40299676, 2025). "Hyperlipidemia associated with elevated TG and an increased TG/HDL ratio is being increasingly recognized as a significant atherosclerotic CVD risk, beyond the risk posed by elevated LDL-C and ApoB concentrations." (PMID 35307397, 2022). "In summary, AKT1, TNF, PPARG, ADIPOQ, and APOB may be targets for the action of DO in the treatment of hyperlipidemia." (PMID 35502176, 2022). "Interestingly, validation in both WT and ApoE−/− mice revealed ApoB reactive memory T-cells are progressively activated in conditions of hyperlipidemia, and that their existence predates the onset of atherosclerotic disease." (PMID 35419441, 2022). "The manifestations of FCHL are heterogeneous, the disease may manifest itself in the form of mixed hyperlipidemia, isolated hypercholesterolemia, hypertriglyceridemia or in combination with elevated ApoB levels." (PMID 35743896, 2022). "Serum apolipoprotein B concentration is a key indicator for the diagnosis of hyperlipidemia." (PMID 36568987, 2022). "Hyperinsulinemia may increase apolipoprotein B-48 secretion by stimulating chylomicrons formation in the small intestine and inducing postprandial hyperlipidemia." (PMID 34932697, 2021). "Paradoxical to the generally accepted association between hyperlipidemia and gallstones, we observed that lower levels of TC, LDL, and APOB, characteristic of hypolipidemia, were also associated with biliary stones independent of the other lipids and risk factors we examined." (PMID 32192520, 2020). "In addition, ART-associated hyperlipidemia can present as TC, high TG, increased plasma LDL-C, increased VLDL, increased apoB, and variable levels of plasma HDL-C." (PMID 29290955, 2017). "We reported that fasting serum concentrations of remnant lipoproteins and apolipoprotein B-48 (apoB-48) besides TG might indicate postprandial hyperlipidemia even among normolipidemic individuals." (PMID 23110373, 2012). "In the apoB gene we only looked for the R3500Q mutation, and the possibility that other mutations in that gene are responsible for hyperlipidemia cannot be ruled out." (PMID 15701167, 2005). "However, while these alterations are well accepted and APOB-100 mice serve as a validated model of human hyperlipidemia and atherosclerosis, much less is known about the functional and morphological alterations induced by an HFD in other tissues in these transgenic mice." (PMID 33919597, 2021). "In a previous experimental study, the component of basal linear deposit and subretinal drusenoid deposit in AMD contain the apolipoprotein B,E-containing, cholesterol-rich lipoproteins, and the hyperlipidemia may accelerate this process and lead to the occurrence of AMD." (PMID 33401577, 2021). "In summary, the results of the present meta-analysis revealed that the C allele of APOA5 1131 T > C, the A allele at APOA1-75 bp, the APOB XbaI T allele, and the ε2 and ε4 alleles of APOE may represent genetic risk factors for susceptibility for hyperlipidemia." (PMID 33836655, 2021). "Therefore, decreased ApoA1 and increased ApoB are the manifestation of hyperlipidemia." (PMID 30231880, 2018).
hyperlipidemia (continued). "Compared with the T2D group, the T2D with hyperlipidemia group had significantly higher levels of TG, TC, LDL-C, ApoB/ ApoA1, FBG, HbA1c, hs-CRP, and PCSK9." (PMID 39951410, 2025). "Herein, we report three potential drug-targeting proteins for hyperlipidemia: PCSK9, APOB, and NCAN." (PMID 39474612, 2024). "After exploring the PPI network of DO for hyperlipidemia, the key targets of DO for hyperlipidemia included AKT1, TNF, PPARG, ADIPOQ, and APOB." (PMID 35502176, 2022). "A meta-analysis was conducted to explore the relationship between APOA (A1-75bp, A1 + 83 bp, A5–1131T>C), APOB (MspI, XbaI, EcorI), and APOE with hyperlipidemia so that an evidence-base can be provided for the prevention and control of hyperlipidemia." (PMID 33836655, 2021). "RYR is effective in reducing TC, TG, LDL-C, apoB and increasing HDL-C in patients with hyperlipidemia, and has an especially large positive impact on TG." (PMID 35111069, 2021). "It is well accepted that oversecretion of apoB—containing lipoproteins, chylomicrons from the intestine and VLDL from the liver, contributes to hyperlipidemia and cardiovascular complications." (PMID 28677105, 2018). "Compared with the healthy controls, patients with hyperlipidaemia had higher systolic blood pressure (SBP), diastolic blood pressure (DBP), CR, TC, TG, apoA-I and apoB, and lower HDL-C." (PMID 27633510, 2016). "In the lipid system, the blood chemistry data showed that steroid hormone administration (model group) induced marked hyperlipidemia, such as significantly elevated TG, TC, LDL, ApoA1, and ApoB levels, but significantly decreased HDL levels." (PMID 25759816, 2015). "Administration of 10–22.5 g/kg ABE dose-dependently improved hyperlipidemia by decreasing TG (P <0.01), TC (P <0.01), LDL (P <0.05), ApoA1 (P <0.05), and ApoB (P <0.05) levels, and increasing HDL levels (P <0.05)." (PMID 25471933, 2014). "In our cohort, plasma IL-22 levels were significantly reduced in hyperlipidemia and inversely correlated with TC, TG, non-HDL-C, and ApoB, while positively associated with HDL-C." (PMID 41415268, 2025). "Notably, dietary intervention with AGBR reduced TG, TC, LDL-c, and apolipoprotein-B levels and elevated HDL-c and apolipoprotein-A1 levels in patients with hyperlipidemia." (PMID 38826585, 2024). "APOB deficiency should be suspected in patients with NAFLD in the absence of hyperlipidaemia, in whom circulating APOB levels should be examined." (PMID 36937991, 2023). "It has been shown that ezetimibe monotherapy decreases total cholesterol, LDL-C, apolipoprotein B, and non-high density lipoprotein cholesterol levels in hyperlipidemia patients." (PMID 36015103, 2022). "The network analysis uncovered that naringenin, isorhamnetin, and taxifolin might be the compounds in DO that are mainly in charge of its roles in hyperlipidemia and might play a role by modulating the targets (including PPARG, ADIPOQ, AKT1, TNF, and APOB)." (PMID 35502176, 2022). "Additionally, RYR significantly reduced apoB (MD, −27.98; 95% CI, −35.51 to −20.45; p < 0.00001) and, whether alone or in combination, did not increase the risk of adverse events in patients with hyperlipidemia." (PMID 35111069, 2021).
hyperlipidemia (continued). "Four representational genes, including Apolipoprotein B gene (APOB), Carboxylesterase 1 gene (CES1), Delta Like Non-Canonical Notch Ligand 1 gene (DLK1), Lipase Maturation Factor 1, (LMF1), were contributed to hyperlipidemia." (PMID 27888796, 2016). "More interestingly, doses of 20~40 mg/kg TMP could improve hyperlipidemia by decreasing TG, TC, LDL, ApoA1, and ApoB levels and increasing HDL levels." (PMID 25759816, 2015). "The differences in age, gender, serum LDL-C and ApoB levels, and the percentages of subjects who had hyperlipidemia and smoked cigarettes were not significant between the control and patient groups (P > 0.05)." (PMID 26204962, 2015). "Also, a recent study demonstrated that DHA attenuates postprandial hyperlipidemia in a PPARα dependent manner by activation of fatty acid oxidation genes in the intestine leading to decreased TAG and apoB secretion." (PMID 24834104, 2014). "Although the fasting adiponectin concentration correlates with the fasting values of TG, RemL-C, RLP-C, RLP-TG and TG/apoB, it is not a significant predictor of postprandial hyperlipidemia in multivariable linear regression analysis." (PMID 23110373, 2012). "Although fasting adiponectin concentration correlated with the iAUCs for TG, RemL-C, RLP-C, RLP-TG, and TG/apoB, it was not a significant predictor of postprandial hyperlipidemia in multivariable linear regression analysis." (PMID 23110373, 2012). "Familial combined hyperlipidaemia is characterised by overproduction of apolipoprotein B (apo B) containing particles by the liver, but there is no diagnostic genetic test." (PMID 17173705, 2006). "The present study demonstrated a significant upregulation in several apolipoproteins, including APOC1, APOB, APOC4 and APOL1, but also in LCAT, suggesting a dysregulation in lipoprotein metabolism that could be partially related to the hyperlipidemia in IMN patients." (PMID 37511514, 2023). "Expression of hepatic genes involved in cholesterol metabolism (SREBP2, HMGCR, and ApoB) and lipogenesis (SREPB1c, SCD-1, FAS, and Acacα) was suppressed in the experimental group, and may have favorably affected hyperlipidemia and hepatic steatosis induced by the high-fat diet." (PMID 22027268, 2011). "Patients with T2DM have been reported to exhibit elevated apolipoprotein B (ApoB) and non-esterified fatty acids (NEFAs) levels, as well as increased production and delayed catabolism of lipoproteins, for example, chylomicron, leading to postprandial hyperlipidemia." (PMID 38890991, 2024). "In summary, lipid may be the key factor causing VCI in the infarction patients, hyperlipidemia was less common in VCI compared with stroke without dementia, and to our best knowledge, this article is the first ever to present the ratio of apoB/LDL as a possible clinical index for VCI." (PMID 27887584, 2016). "Tafolecimab is a valuable treatment option for hyperlipidemia, which showed improvement in several lipid indices (LDL, LDL-C, LDL CFB, non-HDL-C CFB, and apolipoprotein B CFB)." (PMID 40478366, 2025). "TAO patients with hyperlipidemia exhibited higher TC, TG, LDL-c, apolipoprotein A (ApoA), apolipoprotein B (ApoB), and apolipoprotein E (ApoE) levels, as well as lower HDL-c levels, compared with TAO patients without hyperlipidemia (p < 0.05)." (PMID 39669501, 2024). "While this study did not include subjects with hyperlipidemia or hypertriglyceridemia, both the overweight and lean NAFLD groups showed significantly higher levels of serum LDL, TC, TG, APOB, and lower levels of HDL and APOA1 than their healthy counterparts." (PMID 38034020, 2023). "Ezetimibe decreases raised levels of high total cholesterol (total-C), low density lipoprotein cholesterol (LDL-C), apolipoprotein B (Apo B), and non-high density lipoprotein cholesterol (non HDL-C) in patients with hyperlipidemia." (PMID 33803259, 2021).